TNF (tumor necrosis factor)
Diseases named in the same sentence as TNF in open-access papers (continued):
Sharing a sentence is not in itself a finding about the gene and the disease.
asthma (continued). "This is significant since the TNF-α axis does have a role in asthma that is refractory to current therapy, and TNF-α levels in bronchoalveolar lavage (BAL) fluid are elevated in patients with severe asthma." (PMID 29576747, 2018). "Human clinical trials with anti-TNF-α-immunomodulators (etanercept) and anti-TNF-α monoclonal antibodies (infliximab) have shown that TNF-α has a role in asthma that is refractory to corticosteroids." (PMID 29576747, 2018). "TNF-α was an important pleiotropic cytokine in patients with asthma, and played a key role in airways hyperresponsiveness and other asthma features." (PMID 29751569, 2018). "Among other things, the affected patients suffered from infections and various tumors – side effects making impossible the broad use of TNF-α antagonists for asthma therapy." (PMID 31826038, 2018). "The TNF signaling in airway ECs promoted Th2; however, TNF was dispensable for allergic airway disease in a protease-mediated model of asthma." (PMID 29867994, 2018). "The anti-TNF-α drugs were still controversial for the treatment of asthma, the application of treatment for asthma should have been done more carefully, and this therapy should have been used for particular populations." (PMID 29751569, 2018). "Elevated concentration of TNF-α is detected in people with symptomatic and asymptomatic asthma after allergen exposure." (PMID 30412632, 2018). "The related studies and investigators have shown that anti-TNF-α drugs are beneficial for the subset of patients who have a high TNF-α level in airways with severe asthma." (PMID 29751569, 2018). "The activity of p38 MAP kinases is, in turn, induced by inflammatory mediators including TNF (tumor necrosis factor), which is also involved in asthma pathogenesis." (PMID 30257479, 2018). "There were even reports regarding etanercept and adalimumab -induced asthma for patients using these TNF-alpha inhibitors for other indications." (PMID 30059516, 2018). "The levels of the TNF-α protein and messenger RNA (mRNA) in patients with severe asthma were elevated, and the TNF-α promoted airway inflammation and airway hyperresponsiveness (AHR), which play a central role in airway remodeling." (PMID 29751569, 2018). "Increased expression of nasal epithelial TNF has also been reported in children and adolescents with asthma whose nasal microbiome was enriched for M. catarrhalis." (PMID 29885665, 2018). "Evidence shows that TNF-α plays a critical role in the initiation and elevation of airway inflammation in patients with asthma." (PMID 30233389, 2018). "In asthma, TNF is shown to synergize with IL-17 by promoting neutrophil recruitment, whereas in atopic dermatitis, TNF is responsible for the production of other cytokines, including IL-32 which induces keratinocyte apoptosis." (PMID 30473698, 2018). "For diagnosing acute asthma attacks, the AUC of the miR-1 expression level was the highest (AUC = 0.900, P < 0.05), followed by the TNF-α level (AUC = 0.837, P < 0.05) and the IFN-γ level (AUC = 0.823, P < 0.05)." (PMID 30046607, 2018). "In severe asthma, TNF-α also recruited neutrophils, induced resistance to glucocorticoids, and stimulated fibroblast growth." (PMID 29751569, 2018). "The cytokines that are secreted by the inflammatory cells, including interleukins, chemokines, and tumor necrosis factor, are involved in triggering asthma and promote chronic airway inflammation." (PMID 29751569, 2018). "In particular, CREB phosphorylation through p38 MAP kinases after TNF stimulation was demonstrated in human airway epithelial cells and in primary lung fibroblasts in asthma patients." (PMID 30257479, 2018). "Genome-wide expression profile studies have been conducted to assess some asthma-susceptible genes that are related to smoke exposure, such as ADAM33, TNF, GSTP1, GSTM1, and GSTT1." (PMID 29751569, 2018).
asthma (continued). "Severe asthma in human subjects and in animal models has been correlated with increased levels of TNF-α in bronchoalveolar lavage and lung biopsies." (PMID 30300399, 2018). "On the other hand, the systemic inflammation with increased production of IL-1, IL-6, or TNF-α has an effect on the various processes in asthma, such as recruitment and adhesion of eosinophil to airway epithelial cells and bronchoconstriction." (PMID 29951106, 2018). "Biomarkers of stress involved in systemic inflammation, such as TNF-α, have been shown to be elevated in acute asthma exacerbations in comparison to individuals with well controlled asthma." (PMID 28609485, 2017). "In asthma, IL-6 and TNFα positively correlated with the endogenous thrombin potential (β = 0.35 [95% CI, 0.28–0.42] and β = 0.15 [95% CI, 0.07–0.23], respectively) but not with CLT or platelet markers." (PMID 28429138, 2017). "Mast cells respond to inflammatory inducers in the early phase and release TNF-α to bring on typical asthma characteristics, such as contracting smooth muscles, attracting neutrophils and eosinophils, and activating T cells." (PMID 29151835, 2017). "Blocking TNF-alpha in severe asthma has been met with variable successes but an unacceptable risk-benefit ratio which has also led to a lack of further clinical development for asthma." (PMID 28855973, 2017). "Selected characteristics of participants with TNF-α high and low asthma are reported in the supplement and displayed in S2 Table." (PMID 28609485, 2017). "In acute model of asthma, the levels of TNF-α (p < 0.05) and IL-6 (p < 0.01) in BALF obtained from OVA-treated mice were higher as compared to control mice." (PMID 28293189, 2017). "In asthma model of chronic allergic airway inflammation, the TNF-α (p < 0.05) and IL-6 (p < 0.01)levels were reduced in BALF and lung homogenate on treatment with kinase inhibitor." (PMID 28293189, 2017). "In Th17+ and neutrophil-dominant, steroid-resistant asthma, TNF-α inhibitors have protective functions, significantly suppressing pulmonary inflammation, improving lung compliance and reducing neutrophil cytokine secretion and neutrophil infiltration." (PMID 29359169, 2017). "A weak inverse relationship was documented for TNFα and plasminogen in asthma (β = −0.1 [95% CI, −0.18 to −0.03]) and in the controls (β = −0.26 [95% CI, −0.38 to −0.15])." (PMID 28429138, 2017). "We found BDR to be increased in participants who self-reported racial/ethnic discrimination with this increase being greater among African American youth with TNF-α high asthma, an asthma type thought to be resistant to traditional asthma medications." (PMID 28609485, 2017). "Mean difference in bronchodilator responsea and 95% CI for reports of racial/ethnic discrimination and according to TNF-α status for SAGE II participants with asthma (2006–2014)." (PMID 28609485, 2017). "In contrast, GRdim mice are prone to develop systemic inflammation after challenge with lipopolysaccharide (LPS) or tumor necrosis factor alpha (TNFα) and are refractory to GC treatment of RA and asthma." (PMID 28837059, 2017). "This supports the theory that asthma is heterogeneous and that this heterogeneity extends to the endotypes already identified, such as TNF-α asthma." (PMID 28609485, 2017). "Our findings of increased bronchodilator response in those with high TNF-α high asthma plus self-reported racial/ethnic discrimination should be taken in this context." (PMID 28609485, 2017). "The clinical use of TNF-α inhibitors in the treatment of obstructive lung diseases such as asthma and chronic obstructive pulmonary disease is controversial and has been reported to be associated with potential adverse side effects." (PMID 28912506, 2017). "We previously reported a correlation between TNF-α gene expression and protein levels and the induction of asthma." (PMID 29151835, 2017).
asthma (continued). "Gene-environment interactions between air pollution and SNPs in GSTP1 (rs1138272 and rs1695) and TNF (rs1800629) on asthma were investigated." (PMID 29246113, 2017). "Changes in Th17 cells correlate with asthma induction, making it important to analyze Th-17 proteins such as TNF-α, IL-6, and IL-1β." (PMID 29151835, 2017). "Cytokines thought to be important in the pathogenesis of neutrophilic T2-lo asthma include interleukins (IL)-1, 8, 23 and 17 and TNF-alpha." (PMID 28855973, 2017). "IL-1, TNF-a, and IL-6 are considered to be expressed in most types of inflammation, especially asthma." (PMID 29250125, 2017). "In asthma, we demonstrated 62% higher plasma levels of IL-6 and 35% higher TNFα, also after adjustment for potential confounders (β = 0.43 [95% CI, 0.37–0.49] and β = 0.37 [95% CI, 0.31–0.43], respectively)." (PMID 28429138, 2017). "An important role of TNFα in the pathogenesis of allergic inflammatory diseases such as asthma has been extensively documented." (PMID 28659824, 2017). "GAC1 was demonstrated to inhibit the release of TNF-α in LPS-stimulated murine macrophages and asthma patients’ peripheral blood mononuclear cells (PBMNCs)." (PMID 29344411, 2017). "The contradicting reports about efficiency and safety of TNF-α blockers in animal models and patients with severe asthma prompted us to study the effect of TNF-α neutralization during pulmonary infection and exacerbation of AAI." (PMID 29184554, 2017). "Among these cytokines, IL-1, IL-6, and TNF-α are considered to be involved in various inflammatory diseases including asthma and chronic pulmonary disease (COPD)." (PMID 28116321, 2016). "According to the results, IL-4 and TNF-α of asthma mice were increased, compared with the blank control group (P < 0.05), suggesting that IL-4 and TNF-α participate in the onset of asthma." (PMID 27143988, 2016). "Several cytokines involved in many cases of asthma such as interleukin (IL)-13 and tumor necrosis factor-α (TNF-α) alter the properties of ASM through effects on calcium signaling." (PMID 26998246, 2016). "TNF-α is increased in the sputum of patients with asthma, aggrevates AHR as well as recruit inflammatory cells in animals." (PMID 27617014, 2016). "In severe refractory asthma, TNFα is able to prolong eosinophils survival by inhibiting apoptosis and thus exacerbating the pathology." (PMID 28025644, 2016). "In vitro NOX4 expression was increased in airway smooth muscle cells from subjects with COPD (n = 5) compared to asthma (n = 7) and upregulated following TNF-α stimulation." (PMID 27435477, 2016). "TNF-a gene codes for a highly pro-inflammatory cytokine involved in many pathophysiological mechanisms of asthma." (PMID 27411394, 2016). "Tumor necrosis factor alpha (TNF-α) is a potent proinflammatory cytokine that plays a significant role in the pathogenesis of asthma by inducing hyperresponsiveness and airway remodeling." (PMID 27445440, 2016). "Pharmacological therapies using specific receptors IL-4, IL-5, TNF and IL-1β blockers are likely to constitute a considerable development in asthma management." (PMID 27536321, 2016). "Many drugs including corticosteroids and the TNF-α antibody infliximab were used for Asthma therapy via reducing macrophage-mediated inflammation." (PMID 27793052, 2016). "In the model of emphysema used in the present study, LASSBio-596 reduced TNF-α, which is consistent with previous studies in models of acute lung injury and asthma." (PMID 26483698, 2015). "Tumor necrosis factor (TNF) is a well characterized proinflammatory cytokine that plays a central role in asthma pathogenesis through direct immunomodulatory actions on ASMC." (PMID 26644796, 2015). "Although clinical studies using antibodies against TNFα to treat asthma has shown variable, the initial clinical studies using TNFα-antibodies showed improved effect specifically on AHR." (PMID 26494305, 2015).
asthma (continued). "In many studies, anti-TNF-α therapy has been used as a strategy for the treatment of asthma and this TNF-α blockade attenuates the production of proinflammatory cell infiltrations in BAL fluid, and airway remodeling and function in mouse models of asthma." (PMID 25658739, 2015). "The role of DNA methylation of TNFα with asthma was further replicated in the Isle of Wight birth cohort for children with a specific TNFα polymorphism." (PMID 25960783, 2015). "Since TNF is one of the critical proinflammatory effector cytokines in asthma, and has been shown to induce multiple inflammatory genes in HASMC, we further characterized the kinetic of TNF induced PTX3 mRNA expression using quantitative real-time RT-PCR." (PMID 26644796, 2015). "Previously, we identified that TNF-α plays an important role in the etiology of asthma and alveolar macrophages can produce large amounts of TNF-α in the lung environment." (PMID 25658739, 2015). "TNF-α is a major mediator of severe asthma, and it is demonstrated that soluble TNFR and antibodies against TNF-α are effective in animal models of asthma and CBD reduced the levels of TNF-α in our model." (PMID 26101464, 2015). "A wealth of inflammatory mediators, particularly the Th2-associated cytokines IL-4, IL-5, and IL-13, and the pro-inflammatory mediator TNF-α, contributed substantially to airway inflammation in asthma." (PMID 26343632, 2015). "C3a mediate synthesis of IL-6 and TNF-α from B cells and monocytes, and IL-17A from Th17 cells, which control the severity of experimental asthma." (PMID 26289385, 2015). "Considering the findings in this article, the effects of anti–IL-1β and anti-TNF therapy on interferon responses and asthma exacerbation rates and severity are warranted and would be of interest." (PMID 25630941, 2015). "Follow-up qPCR and individual analyte ELISA experiments were conducted for four cytokines (i.e. CCL2, CCL13, CXCL12, IL8) to measure TNFα-induced changes by asthma status and vitamin D treatment." (PMID 26207385, 2015). "Overall, our results suggest a role of TGF-β1 in olive pollen sensitization and TNF-α and IL-10 genotypes in the asthma induced by specific olive pollen allergens." (PMID 25759826, 2014). "So we supposed that some SNPs of TNF-α region derived from GWAS may be potentially associated with risk of asthma, expanding the screen criteria at the first step of GWAS may improve the power of test, to generate more SNPs associated with asthma, possibly including TNF-α rs1800629." (PMID 24936650, 2014). "Consistent with this, there is evidence in treatment–resistant severe asthma of increased TNF- α gene and protein expression within the airways compared to that in mild asthma." (PMID 24955983, 2014). "As interesting targets and starting point for experiments we selected Tumor Necrosis Factor alpha (TNFα, MW = 17 kDa) and Interleucin-6 (IL-6, MW = 20 kDa) as they are, among other cytokines, involved in asthma and COPD development." (PMID 27600349, 2014). "Because previous studies showed MAPKs to be involved not only in TNF-α-induced IL-8 production, but also in steroid-resistant inflammation in severe asthma, we focused on this signaling." (PMID 25501580, 2014). "Strong pro-inflammatory and Th2-associated cytokines; including interleukin-1β (IL-1β), IL-4, IL-5, IL-6, IL-9, IL-13, IL-17, IL-25 and tumor necrosis factor α (TNF-α) were reported to enhance asthma." (PMID 24735374, 2014). "The importance of TNF in severe corticoresistant asthma was also suggested by increased protein and gene expression in the airways." (PMID 25371053, 2014). "In our study, it has been found that BMMCs from asthma rat models had many differences compared to normal rats, including higher levels of β-hexosaminidase released and higher cytokines (IL-6, IL-13, TNF-α, histamine) secreted." (PMID 24995695, 2014).
asthma (continued). "Th2 cells, which are characterized by IL-4, IL-5, IL-9 and IL-13 cytokine production, predominate in asthma, whereas Th1 cells producing IFN-γ, IL-2 and TNF have rarely been associated with asthma." (PMID 25132806, 2014). "The results demonstrated that the levels of IL-4 and TNF-α in the sihuangxiechai decoction treated group were significantly reduced compared with the asthma group." (PMID 25101137, 2014). "There is significant literature to support a pathologic role for TNF-α in asthma, especially in severe refractory asthma and COPD." (PMID 24587316, 2014). "The OVA-induced asthma group significantly increased the concentrations of TNF-α and IL-4 in BALF in comparison to the normal group (P < 0.01, P < 0.01)." (PMID 25101137, 2014). "Clinical observation and animal experimentation indicated that the content of TNF-α in BALF was elevated when asthma attacks." (PMID 25101137, 2014). "IL-33 and TNF-α expression in lung tissues from asthmatic subjects increases with the severity of asthma." (PMID 24822215, 2014). "In conclusion, these results suggest a role of TGF-β1 in olive-pollen sensitization and TNF-α and IL-10 genotypes in the asthma induced by specific olive-pollen allergens." (PMID 25759826, 2014). "Airway smooth muscle cell proliferation in asthma is regulated by the proinflammatory cytokines including IL-1β and TNF-α." (PMID 23388501, 2013). "In cells from normal individuals, RV infection induced secretion of CXCL10 and TNFα; these responses were significantly blunted in the asthma group." (PMID 24219422, 2013). "A substantial documentary evidence supports IL-1β and TNF-α as a central players in the pathogenesis and progression of asthma; they are also common in any inflammatory disorder, and can act both locally and systemically." (PMID 23388501, 2013). "Etanercept a recombinant fusion protein that blocks TNF-α, produces marked and significant improvement in asthma control when added to high-dose ICS therapy in patients with treatment-resistant asthma." (PMID 23388501, 2013). "Elevated levels of IL-1β and TNF-α are reported from BAL fluid of asthma patients and they increase with severity of disease." (PMID 23388501, 2013). "TNF-α also is up-regulated in asthma and promotes recruitment of neutrophils and eosinophils into the airways." (PMID 23388501, 2013). "It was also reported that the expression of proinflammatory cytokine TNFα mRNA was strongly related to the NF-κB activation in asthma and COPD patients." (PMID 27234389, 2013). "TNF-α is overexpressed in the airways of patients with severe asthma and also directly stimulates airway smooth muscle contraction through changes in intracellular calcium fluxes." (PMID 23853765, 2013). "The proinflammatory cytokines tumor necrosis factor α (TNFα) and interferon γ (IFNγ) are increased in asthma and have been shown to contribute to apoptosis at the airways." (PMID 24303189, 2013). "The study revealed multiple SNPs and haplotypes in LTA4H, TNFα and IL4-Rα genes which constitute risk factors for the development of difficult asthma in children." (PMID 23573270, 2013). "In particular, the occurrence of dramatic adverse events including serious infections and neoplastic disorders, observed during treatment with golimumab, currently discourages the further development of anti-TNF-α strategies for asthma therapy." (PMID 23853765, 2013). "It is of interest that previously a positive correlation between IL-33 and TNF-α expression in the lung tissues in patients with asthma has been described suggesting a role of IL-33 in the pathogenesis of that disease." (PMID 23567618, 2013). "The anti-TNF-α monoclonal antibody infliximab shows positive outcomes in moderate asthma despite ICS therapy." (PMID 23388501, 2013). "TNF-α is expressed in biopsies and lavage fluid from asthmatic airways, particularly in patients with severe asthma compared with those with well-controlled disease." (PMID 23189057, 2012).